THPO (thrombopoietin)
Diseases named in the same sentence as THPO in open-access papers (continued):
Sharing a sentence is not in itself a finding about the gene and the disease.
aplastic anemia (21 papers, 2013 to 2025). Anemia resulting from bone marrow failure (aplastic or hypoplastic bone marrow). "The first homozygous loss‐of‐function variant of THPO (p.R38C) was reported in a Micronesian family presenting with a recessive form of aplastic anemia." (PMID 29191945, 2018). "A homozygous missense mutation in THPO (p.R38C) was previously reported in a family with a recessive form of aplastic anemia." (PMID 29191945, 2018). "While early trials of THPO mimetics in primary and acquired aplastic anemia have been promising, to our knowledge, no group has specifically studied their use in liver failure-associated aplastic anemia." (PMID 34463253, 2021). "Homozygous mutations in THPO can result in CAMT that evolves rapidly to aplastic anemia." (PMID 29191946, 2018). "The use of romiplostim, a thrombopoietin agonist, has increased in the last decade for the treatment of immune mediated thrombocytopenia and severe aplastic anemia." (PMID 41254453, 2025). "We compared recombinant human thrombopoietin (rh-TPO) with early AVA switching for treating DPE in aplastic anemia (AA) patients post-allo-HSCT to optimize management strategies." (PMID 40861202, 2025). "In the 2017 report we described lower rates of aplastic anemia transplantation possibly due to the use of thrombopoietin analogues such as eltrombopag." (PMID 33623153, 2021). "Last year, we reported lower rates of aplastic anemia transplantation possibly due to the use of thrombopoietin analogs such as eltrombopag." (PMID 32066864, 2020). "Patients with aplastic anemia have the highest levels of blood thrombopoietin (~1-2 ng/ml) with normal values of approximately 80 pg/ml." (PMID 27766065, 2016). "Recombinant human thrombopoietin (rhTPO) regulates platelet production by promoting megakaryocyte proliferation and has shown promising therapeutic effects in hematopoietic recovery for severe aplastic anemia (SAA)." (PMID 40926984, 2025). "TPO-RAs have been found to improve trilineage hematopoiesis in aplastic anemia patients despite the presence of high levels of endogenous thrombopoietin, which suggests that analogs may exert this effect using alternative anti-inflammatory mechanisms." (PMID 39274330, 2024). "Moreover, because of the effects of thrombopoietin on HSCs, clinical trials of the drug were also conducted in patients with severe aplastic anemia (SAA)." (PMID 38672505, 2024). "Moreover, eltrombopag is a thrombopoietin (TPO) receptor agonist for the treatment of aplastic anemia and chemotherapy-induced thrombocytopenic patients." (PMID 37251921, 2023). "Indeed, treatment of aplastic anemia patients with thrombopoietin mimetics, such as eltrombopag and romiplostim, have demonstrated clinical efficacy." (PMID 26147434, 2015). "Indeed, THPO mimetic drugs, such as romiplostim and eltrombopag, have been shown to improve recovery after ablative challenge, and have also been used clinically to support hematopoiesis in diseases such as immune thrombocytopenic purpura and aplastic anemia." (PMID 34463253, 2021). "Of note, the remaining patient was diagnosed with severe aplastic anemia (AAS) refractory to both immunosuppressive therapy and thrombopoietin analog." (PMID 34093576, 2021).
immune thrombocytopenia (21 papers, 2014 to 2025). "Patients with idiopathic thrombocytopenic purpura coexisted with antiphospholipid antibody syndrome are at increased risk of thrombosis with thrombopoietin agonists and require careful follow-up." (PMID 39830571, 2024). "Recombinant human thrombopoietin (rhTPO) at a fixed dose of 300 U/kg/day for 2 weeks has demonstrated good efficacy and safety in adults with immune thrombocytopenia (ITP)." (PMID 40896456, 2025). "These megakaryocytes are often seen in MPN as well as in thrombopoietin agonist stimulation and in some cases of immune thrombocytopenia." (PMID 37814319, 2023). "QL0911, a recombinant human thrombopoietin mimetic peptide-Fc fusion protein, is a romiplostim (Nplate®) biosimilar used to treat primary immune thrombocytopenia (ITP)." (PMID 38130645, 2023). "The anti-THPO antibody was reported to be found in patients with amegakaryocytic thrombocytopenic purpura, idiopathic thrombocytopenia purpura (ITP), systemic lupus erythematosus (SLE), in those treated with rhTHPO and recombinant human erythropoietin." (PMID 32260359, 2020). "In models of acute immune thrombocytopenia or non-immune thrombocytopenia, platelet counts are inversely related to plasma thrombopoietin levels, which are elevated independently of hepatic Thpo mRNA levels." (PMID 32479494, 2020). "Eltrombopag is an oral thrombopoietin (TPO) receptor agonist that increases platelet counts in patients with idiopathic thrombocytopenic purpura and in patients with liver cirrhosis." (PMID 24932302, 2014). "Eltrombopag is an oral thrombopoietin (TPO)-receptor (R) agonist that stimulates megakaryocytes and thus, increases platelet counts in patients with idiopathic thrombocytopenic purpura." (PMID 24932302, 2014). "Immune thrombocytopenia, for instance, can be treated with a thrombopoietin (TPO) analogue, addressing both the increased demand on platelet production posed by the immune thrombocytopenia (ITP) and the platelet production deficit directly related to dysmegakaryopoiesis as a feature of CMML." (PMID 40556336, 2025). "Hetrombopag as the derivative of ethylidene hydrazine carboxamide was recently developed into a novel patented non-peptide thrombopoietin mimetic and thrombopoietin receptor agonist to treat idiopathic thrombocytopenic purpura." (PMID 26543786, 2015). "Immune thrombocytopenia (ITP) may occur in variable pathways as a result of cross-reacting antibodies or immune complexes that bind to platelet receptors, or infection of progenitor megakaryocytes, and decreased production of thrombopoietin (TPO)." (PMID 37034371, 2022).
Sepsis (21 papers, 2013 to 2025). Sepsis is defined as life-threatening organ dysfunction caused by a dysregulated host response to infection. "Increased THPO levels have been shown in different clinical conditions characterized by a pro-thrombotic state, from acute coronary syndromes to sepsis/septic shock and cigarette smoking, and are associated with elevated indices of platelet activation." (PMID 34210000, 2021). "Increased THPO levels have been reported in different clinical conditions characterized by a generalized pro-thrombotic state, from acute coronary syndromes to sepsis/septic shock, and associated with elevated indices of platelet activation." (PMID 34210000, 2021). "Sepsis is usually associated with an increase in thrombopoietin levels to compensate for platelet consumption due to an inflammatory condition." (PMID 32751801, 2020). "Some studies showed that for sepsis-associated thrombocytopenia, TPO treatment improved platelet count and reduced platelet transfusion; however, other studies showed that blocking thrombopoietin reduced organ damage associated with sepsis." (PMID 32241296, 2020). "Meanwhile, another research proposed an increased production of thrombocytes in sepsis, as evidenced by increased values of thrombopoietin in septic patients." (PMID 39417064, 2024). "Elevated thrombopoietin levels have been reported in healthy volunteers after endotoxin infusion as well as in children and adults with sepsis." (PMID 29381746, 2018). "Tumor necrosis factor-α and IL-6 are secreted as initial proinflammatory cytokines in sepsis, stimulating the production of thrombopoietin." (PMID 29381746, 2018). "Regulators of thrombopoiesis, such as thrombopoietin, tumor necrosis factor-α, and interleukin (IL)-6, all increase in patients with sepsis and correlate with sepsis severity." (PMID 29381746, 2018). "This increase in AIPC on admission reflects increased thrombopoiesis in sepsis, possibly resulting from inflammatory cytokines, including thrombopoietin." (PMID 29381746, 2018). "Importantly, thrombopoiesis is stimulated in sepsis patients, as indicated by an elevated reticulated platelet percentage and circulating thrombopoietin (TPO)." (PMID 40985691, 2025). "This process might in part be driven by increased thrombopoietin levels in the blood of sepsis patients and has previously been acknowledged to be a significant contributing factor in organ failure." (PMID 32318053, 2020). "Thrombopoietin and other stimulators increase in patients with sepsis." (PMID 29381746, 2018). "Thrombopoietin (TPO), a growth factor primarily involved in regulating thrombopoiesis, has recently emerged as a humoral mediator potentially implicated in the pathogenesis of sepsis." (PMID 26963510, 2016). "Results from the current study showed that F.n. infected galectin-3−/− animals exhibited a reduction in the levels of sepsis mediators such as vascular injury markers thrombopoietin, fibrinogen, as well as acute phase protein CRP and inflammatory cytokines such as TNF-α, IL-6 and IL-1." (PMID 23527230, 2013). "Moreover, research on neonatal thrombopoiesis during sepsis strongly suggested that neonates respond to sepsis by upregulating thrombopoietin (Tpo) production; although the degree of upregulation is modest, neonates present with a hypercoagulant profile at the onset of infection." (PMID 35204352, 2022). "In severe sepsis, Antithrombin III, Protein C, C-reactive protein, Procalcitonin and Thrombopoietin had AUROCs 0.73–0.75." (PMID 33917002, 2021). "Thrombopoietin (TPO), a growth factor primarily involved in thrombopoiesis may also have a role in the pathophysiology of sepsis." (PMID 26963510, 2016). "However, no studies except those concerning neonatal sepsis have evaluated the relationship between thrombopoietin and reticulated platelet count, and it is not clear how effectively thrombopoietin increases the production of platelets in the acute phase of sepsis." (PMID 29381746, 2018).
liver cirrhosis (17 papers, 2013 to 2025). "Interestingly, previous studies have shown that serum thrombopoietin levels in very low concentrations decrease slightly as the disease progresses from mild fibrosis to cirrhosis of the liver." (PMID 35204403, 2022). "And, Thrombopoietin (TPO) synthesis in the liver is reduced because of liver cirrhosis which could stimulate platelet formation." (PMID 34277414, 2021). "Our results suggest that liver cirrhosis does not cause impaired thrombopoietin production even in the late stage of disease." (PMID 24976834, 2014). "As a cross-regulatory loop between THPO and VEGF-A has been demonstrated in the hematopoietic system, the two growth factors were hypothesized to cooperatively contribute to the progression from liver cirrhosis (LC) to hepatocellular carcinoma (HCC)." (PMID 33673041, 2021).
ovarian carcinoma (16 papers, 2013 to 2024). A malignant neoplasm originating from the surface ovarian epithelium. "Genes WNT11 and THPO were reported to be associated with ovarian cancer and colorectal cancer, respectively." (PMID 31640538, 2019). "A recent study on ovarian cancer indicated that paraneoplastic thrombocytosis is due to the enhancements induced in hepatic thrombopoietin synthesis by tumor-derived IL-6." (PMID 28903428, 2017). "Recently, plasma levels of IL-6 and thrombopoietin were found to significantly correlate with platelet counts in ovarian cancer patients." (PMID 25469228, 2014). "For example, elevated plasma levels of IL-6 and thrombopoietin were reported in ovarian cancer patients." (PMID 25469228, 2014). "In mouse models bearing human ovarian cancer, human IL-6 was found to stimulate hepatocytes via the IL-6 receptor to produce thrombopoietin." (PMID 23864954, 2013). "Platelet production in the bone marrow is regulated by paracrine signaling between interleukin-6 and thrombopoietin, which could contribute to increased platelet counts in patients with ovarian cancer." (PMID 39518024, 2024). "Interestingly thrombopoietin (TPO) is considered as a biomarker for ovarian cancer, that also regulates expression of PDGFR." (PMID 36615606, 2023). "Thus a model was proposed according to which ovarian cancer tumor cells produce IL-6 which stimulates the liver to produce thrombopoietin, finally resulting in increased thrombopoiesis through stimulation of megakaryocyte progenitors in the bone marrow." (PMID 23864954, 2013). "Because tumor‐derived interleukin (IL)‐6 increases hepatic thrombopoietin synthesis and platelet production, as well as increases thrombotic events in patients with ovarian cancer, it has been suggested that interfering with the IL‐6‐thrombopoietin pathway may reduce VTE events." (PMID 33638309, 2021). "Since mice transplanted with human ovarian cancer cells (SKOV3) demonstrated elevated tumor size and decreased survival rate when treated with thrombin or thrombopoietin (TPO), the platelets appeared to promote primary tumor growth." (PMID 25502723, 2015).
Splenomegaly (16 papers, 2013 to 2025). Abnormal increased size of the spleen. "Similarly, liver dysfunction contributes to platelet dysfunction through multiple mechanisms, including splenomegaly, splenic sequestration, relatively reduced thrombopoietin, consumption owing to autoantibodies, and bone marrow suppression." (PMID 40129657, 2025).
anemia (15 papers, 2008 to 2025). A reduction in the number of red blood cells, the amount of hemoglobin, and/or the volume of packed red blood cells. "Additional causes include disruptions in megakaryocyte development, bone marrow fragmentation, bowel inflammation, interference with thrombopoietin function, anemia, or polycythemia." (PMID 41292546, 2025). "In states of anemia due to chronic disease, reactive thrombocytosis occurs through cytokines such as IL-6 and thrombopoietin." (PMID 35629394, 2022). "Several studies indicate that the Jak/Stat signaling pathway regulates the functions of cytokines, including erythropoietin, thrombopoietin, and granulocyte colony-stimulating factor during the treatment of anemia." (PMID 28683082, 2017).
COVID-19 (13 papers, 2021 to 2025). A disease caused by infection with severe acute respiratory syndrome coronavirus 2. "This can be explained by the presence of inflammation in the lung that leads to the secretion of thrombopoietin, which stimulates platelet production in COVID-19 patients." (PMID 35996516, 2022). "In addition, COVID-19 patients have elevated plasma levels of thrombopoietin, a well-known megakaryocyte growth factor." (PMID 37020458, 2023). "Increased thrombopoietin (TPO) levels have been reported in SARS-CoV infection and more recently in COVID-19 (only in comparison to healthy controls)." (PMID 33596198, 2021). "Strikingly, agonist-induced ADP release was 30- to 90-fold higher in COVID-19 patients compared with hospitalised controls and circulating levels of platelet factor 4 (PF4), soluble P-selectin (sP-selectin), and thrombopoietin (TPO) were also significantly elevated in COVID-19." (PMID 33596198, 2021). "Salmeterol targets on seven non-n-COV host proteins (ADRB1, ADRB2, ADRB3, AOX1, DRD3, KCNH2, and THPO), meaning that it may not act on COVID-19 via directly targeting COV host proteins." (PMID 34539756, 2021).
myelofibrosis (11 papers, 2014 to 2024). A partial or complete replacement of the bone marrow stroma by fibrous tissue. "Mutations in the thrombopoietin gene also cause benign thrombocytosis, although leukemic transformation and myelofibrosis have been observed with this mutation." (PMID 39598101, 2024). "Other alterations affecting hematopoietic cells, such as hypomorphic mutations in the transcription factor GATA1 or high expression of the glycoprotein hormone thrombopoietin (ThPO), cause myelofibrosis in mice." (PMID 39155965, 2024). "In one family, however, such a THPO mutation was also associated with leukemic transformation or myelofibrosis." (PMID 33777803, 2021). "Specifically, in a mouse model of primary myelofibrosis with elevated levels of thrombopoietin (Tpo), MSCs that express the leptin receptor are responsible for forming myofibroblasts within the BM, which is a critical factor in the disease progression." (PMID 38314300, 2024). "Thrombopoietin production is constitutive and normally dependent on metabolism by circulating platelets to maintain its plasma level within the normal range and avoid the pathologic consequences of excess thrombopoietin, such as myelofibrosis." (PMID 39598101, 2024). "In a murine model of thrombopoietin-induced myelofibrosis using Sparc(−/−) mice and BM chimeras, SPARC contributes to the development of significant stromal fibrosis." (PMID 26640324, 2015). "Specifically, in a mouse model of primary myelofibrosis with elevated levels of thrombopoietin (Tpo), MSCs that express the leptin receptor are responsible for forming myofibroblasts within the bone marrow, which is a critical factor in the disease progression." (PMID 38314300, 2024). "In fact, the prevention of thrombopoietin expression in a transgenic mouse model of PV eliminated the PV phenotype, including splenomegaly, myelofibrosis, osteosclerosis, erythrocytosis, leukocytosis, and thrombocytosis, even though the JAK2 V617F mutation was still expressed." (PMID 39598101, 2024). "Murine ThPO and JAK2V617F myelofibrosis models showed co-expression of Nrp2 and Ncam1 in osteolineage cells, while fibrosis-promoting MSC only express Nrp2." (PMID 38792002, 2024). "In chronic myelo-proliferative neoplasms, sustained by enhanced THPO/c-Mpl signaling, a THPOR antagonist (LCP4) has been shown to deplete malignant myelofibrosis in hematopoietic stem and progenitor cells." (PMID 33673041, 2021). "Here we show that OGX-427 is effective in two murine models of thrombopoietin- and JAKV617F-induced myelofibrosis." (PMID 29650953, 2018). "In a study of two mouse models of thrombopoietin and constitutively active JAK2 mutant (JAKV617F)-induced myelofibrosis, HSP27 was found to regulate the proliferation of JAK2V617F-positive cells and interact directly with JAK2/STAT5 to protect STAT5 from dephosphorylation." (PMID 37252119, 2023). "However, whereas in this thrombopoietin-induced myelofibrosis murine model, THBS1 is not required for TGF-β1 activation, it is suggested to be a mediator which discriminates PMF from ET patients within a profibrotic environment." (PMID 26640324, 2015). "Furthermore, the identification of vascular defects in the ThPO and MPL models of myelofibrosis raises the possibility that EndMT, increased biological activity of YAP1/TAZ and SRF-mediated changes in gene expression, but also EC cytoskeletal function, might contribute to fibrosis." (PMID 39155965, 2024).
breast cancer (7 papers, 2014 to 2024). A primary or metastatic malignant neoplasm involving the breast. "We show that whereas firmly adherent platelets continuously line tumor vessels of both AT-3 and B16F1 tumors, abundant extravascular stromal clusters of platelets from thrombopoietin-independent origin were present only in AT-3 mammary tumors." (PMID 38493157, 2024). "For example, thrombopoietin gene silencing can reduce platelet count and breast cancer progression in animal models." (PMID 35205736, 2022). "Thus, conditioned media from AEA-treated breast cancer cells showed an inhibitory effect on endothelial cell proliferation associated with an approximate halving of the VEGF concentration, but also in a significant reduction of other proangiogenic factors such as leptin and thrombopoietin (THPO)." (PMID 35277658, 2022). "In particular, IFNγ, leptin, TGFβ1, TIMP1, TIMP2, thrombopoietin and VEGF levels were significantly inhibited by anandamide in the conditioned medium of MDA-MB-231 breast cancer cells." (PMID 25147760, 2014).